HYAL1 (hyaluronidase 1)
Description:
May have a role in promoting tumor progression. May block the TGFB1-enhanced cell growth.
Synonyms: Hyal-1; LUCA1; MPS9; NAT6
Tractability: Antibody: UniProt places it where antibodies can reach, with high confidence; UniProt predicts a signal peptide or a membrane-spanning region; its Gene Ontology location is reachable by antibodies, with medium confidence. PROTAC: its protein half-life has been measured.
Target class: Enzyme; Hydrolase
Gene: Protein-coding gene on chromosome 3 (50,299,883 to 50,312,890, reverse strand). Ensembl gene ENSG00000114378.
Subcellular location: Secreted; Lysosome
Pathways (Reactome):
Disease: MPS IX - Natowicz syndrome (CS/DS degradation); MPS IX - Natowicz syndrome (Hyaluronan metabolism)
Metabolism: CS/DS degradation; Hyaluronan degradation
Gene Ontology:
Molecular function: hyalurononglucosaminidase activity; virus receptor activity; chondroitin hydrolase activity
Biological process: cartilage development; cellular response to fibroblast growth factor stimulus; cellular response to interleukin-1; cellular response to pH; cellular response to platelet-derived growth factor stimulus; cellular response to tumor necrosis factor; cellular response to UV-B; hyaluronan catabolic process; hyaluronan metabolic process; inflammatory response; negative regulation of cell growth; positive regulation of angiogenesis; positive regulation of cell adhesion; positive regulation of cell growth; positive regulation of hyaluranon cable assembly; response to antibiotic; response to reactive oxygen species; response to virus; chondroitin sulfate proteoglycan catabolic process; carbohydrate metabolic process
Cellular component: cytoplasmic vesicle; extracellular exosome; extracellular region; hyaluranon cable; lysosome; lysosomal lumen
Genetic constraint (gnomAD): Loss-of-function variants: 18 observed, 30.52 expected, observed/expected ratio (o/e) 0.59, 90% interval 0.41 to 0.88. The upper end of that interval is the gene's LOEUF score, 0.88, which puts it in group 3 of 6, group 1 being the genes least tolerant of losing a copy. Missense variants: 491 observed, 605.05 expected, observed/expected ratio (o/e) 0.81, 90% interval 0.75 to 0.87. Synonymous variants: 199 observed, 240.71 expected, observed/expected ratio (o/e) 0.83, 90% interval 0.74 to 0.93.
Gene-disease validity (ClinGen):
ClinGen rates the evidence that HYAL1 causes each of these diseases.
mucopolysaccharidosis type 9 (autosomal recessive): Moderate. An autosomal recessive lysosomal storage disease caused by mutation(s) in the HYAL1 gene, encoding hyaluronidase-1.
Homologues: Orthologues: chimpanzee HYAL1 (99% identical), macaque HYAL1 (97% identical), dog HYAL1 (82% identical), pig HYAL1 (81% identical), rabbit HYAL1 (78% identical), guinea pig HYAL1 (78% identical), rat Hyal1 (74% identical), mouse Hyal1 (73% identical), tropical clawed frog hyal1 (46% identical), zebrafish hyal1 (43% identical), Caenorhabditis elegans chhy-1 (29% identical). Paralogues in human: HYAL2 (41% identical), HYAL4 (40% identical), HYAL3 (39% identical), SPAM1 (38% identical).
Diseases named in the same sentence as HYAL1 in open-access papers:
HYAL1 is named in the same sentence as 110 diseases in open-access papers, as found by Europe PMC text mining. Sharing a sentence is not in itself a finding about the gene and the disease. The quoted sentences say what the papers report.
breast cancer (22 papers, 2010 to 2025). A primary or metastatic malignant neoplasm involving the breast. "Accumulating evidence indicates a positive correlation between HYAL1 levels and the risk of BM formation in breast cancer." (PMID 41421148, 2025). "Beyond this mechanism, several advances have been made in understanding HYAL1 regulation in breast cancer." (PMID 41421148, 2025). "The combined overexpression of HAS and either HYAL1 or HYAL2 is characteristic of the invasive front of human breast cancer." (PMID 37568628, 2023). "In research conducted in vitro and in vivo, tumor cell growth and mobility were increased by forced HYAL-1 expression, while its knockdown reduced the proliferation of breast cancer cell lines." (PMID 36613567, 2022). "Overexpression of HYAL-1 accelerates the development of a mammary tumor and leads to extensive tumor angiogenesis." (PMID 36613567, 2022). "On the other hand, DDIT significantly reduced the expression of hyaluronidases HYAL-2, TMEM2 (encoding the main hyaluronidase expressed in this breast cancer cell line) and KIAA1199/CEMIP, while it enhanced HYAL-1 expression." (PMID 36497283, 2022). "In summary, we show an alteration in mRNA of genes associated with HA metabolism in the colon in correlation analysis, while in breast cancer we observed a decrease in HYAL1 levels." (PMID 32610620, 2020). "In breast cancer samples, the only gene that has consistently lower mRNA expression in TT is HYAL1 (p = 0.0014)." (PMID 32610620, 2020). "HYAL1 knockdown reduces tumorigenicity of breast cancer cell lines, while forced expression of HYAL1 promotes tumor cell growth and migration in culture and in vivo." (PMID 31134064, 2019). "For example, overexpression of HYAL1, one of the major HYALs, results in increased cell proliferation, migration, invasion, and metastasis in prostate and breast cancer." (PMID 28096814, 2016). "Here, we identified the estrogen receptor ERα as a negative regulator of HYAL1 expression in breast cancer cells." (PMID 27764788, 2016). "Overexpression of HYAL1 also induced migration of breast cancer cells and promoted xenograft tumor size and angiogenesis." (PMID 27764788, 2016). "Here, we report a distinct and selective response to estrogen among the 3p21.3 locus genes in breast cancer cells, where the HYAL1 gene was repressed as compared to HYAL2 and HYAL3, and to other genes tested within the cluster." (PMID 27764788, 2016). "This study identifies HYAL1 as an ERα target gene and provides a functional framework for the direct effect of estrogen on 3p21.3 genes in breast cancer cells." (PMID 27764788, 2016). "To investigate the possible regulation of HYAL1 by estrogen, we used human breast cancer MCF-7 cells, which are positive for ER and highly responsive to estrogen." (PMID 27764788, 2016). "Our identification of ERα as a regulatory transcriptional component of the 3p21.3 genes, and in particular of HYAL1, reveals a probable link between breast cancer subtypes and metastatic potential." (PMID 27764788, 2016). "Studies focusing specifically on hyaluronidase 1 (Hyal1) demonstrate that enhanced expression of Hyal1 in breast cancer cells induces tumor cell proliferation, migration, invasion, and angiogenesis." (PMID 26106384, 2015). "The elevated levels of the HA degrading, HYAL1 seems to regulate cell growth, adhesion, invasion, and angiogenesis of breast cancer." (PMID 25140302, 2014). "On the other hand, increased expression of HYAL1 has been reported in prostate cancer and breast cancer." (PMID 24244714, 2013). "In the urothelial carcinoma, prostate adenocarcinoma and breast carcinoma HYAL1 has been considered the mostly expressed tumor-derived hyaluronidase." (PMID 23560496, 2013). "High levels of HYAL-1 expression are also found in breast cancer and glioblastomas, and are correlated with metastatic tumors." (PMID 21695196, 2011).
breast cancer (continued). "In the case of breast cancer, the most promising gene seams to be HYAL1 while BRCA1 and 2 could be considered for further testing in different groups in order to test if it depends on the HER2 or RP status of the patient." (PMID 32610620, 2020). "Consistent with such HYAL1 increase, low molecular weight products of hyaluronan breakdown were enhanced in aggressive breast tumors and ERα-negative cell lines, providing these fragments with a potential clinical value for breast cancer metastasis." (PMID 27764788, 2016). "Similarly, HYAL1 was repressed in human breast cancer BT-474 cells, which also exhibit high expression of ERα." (PMID 27764788, 2016). "In the current study, we show that the HYAL1 gene is a target of ERα in breast cancer cells." (PMID 27764788, 2016). "Integrative data mining analysis was performed to plot the mean values of mRNA expression for ESR1 (ERα gene) and HYAL1 in the whole cohort and in each of the breast cancer subtypes, i.e. luminal A, luminal B, normal-like, basal-like and HER2, as classified by the PAM50 assay." (PMID 27764788, 2016). "Such stratification based on HYAL1 expression in concordance with ERα status in breast cancer subtypes is suggested with our results showing significant lower expression of HYAL1 in breast tumors highly expressing ESR1, such as luminal A and luminal B subtypes." (PMID 27764788, 2016). "Furthermore, knock-down of Hyal1 in breast cancer cells reduces cell growth, adhesion, and invasion in culture as well as decreased tumor growth in vivo." (PMID 26106384, 2015). "In addition, the HYAL1 knockdown showed an inhibition of breast cancer cell xenograft tumor growth and microvessel density, whereas HYAL-1 overexpression demonstrated an increase of tumour growth." (PMID 25126569, 2014). "Interestingly, ER-negative breast cancer cell lines have higher hyaluronidase levels than ER-positive cells and silencing of HYAL1 by RNA interference inhibited cell proliferation and induced cell cycle arrest in some breast cancer cell lines." (PMID 21695196, 2011). "Pathological analysis of clinical samples has shown that HYAL-1 expression is a good prognostic indicator of prostate and bladder cancers, while the analysis of breast cancer cell lines has revealed that highly invasive cancer cells express high levels of HYAL-2." (PMID 24212952, 2011). "Finally, HYAL-1 has been shown to be involved in several biological processes related to tumorigenesis and metastasis such as cell growth, migration, invasion and angiogenesis in breast cancer." (PMID 38256245, 2024). "Interestingly, among the 3p21.3 genes tested, only HYAL1 was found repressed by estrogen, indicating a selective role of these specific ERα binding elements to differentially support the estrogenic response of 3p21.3 genes in breast cancer cells." (PMID 27764788, 2016). "Recent research has demonstrated that HYAL1 and its catalytic product, low-molecular-weight HA (LMW-HA), play crucial roles in forming a pericellular HA coat around breast cancer cells." (PMID 41421148, 2025). "One of the up-regulated genes in the compartment B-to-A switch region was cell migration inducing hyaluronidase 1 (CEMIP), which has been reported to promote the proliferation and migration of breast cancer cells." (PMID 37381036, 2023). "In contrast to our qPCR results, it was reported for breast cancer that HAS2 knockdown in Hs578T cancer cells leads to an upregulation of HAS1, HAS3 and HYAL1." (PMID 35767191, 2022). "Aberrant expression of HYAL1, HYAL2 and SPAM1 has also been reported in breast cancer, and in particular upregulation of HYAL1 was observed in infiltrating invasive duct cancer tissues and metastatic lymph nodes." (PMID 27764788, 2016). "HYAL1 and HYAL2 are found to be overexpressed in breast cancer tumors, downregulating the expression of HA." (PMID 25140302, 2014).
breast cancer (continued). "The most expressed hyaluronidase in breast cancer cells is HYAL-2, even though recent studies showed that HYAL-1 has a pivotal role in tumour cell behaviour and angiogenesis." (PMID 25126569, 2014). "Another study comparing mRNA levels of HA metabolic components between tumor and adjacent non-tumor tissues revealed significantly lower HYAL1 mRNA in breast cancer tissues." (PMID 41421148, 2025). "Interestingly, 4-MU has been shown to reduce HA synthesis and HAS2 and CD44 expression, but increases HYAL1 and HYAL2 in breast cancer cell lines, and to a greater extent in ER− cells." (PMID 37568628, 2023). "Our results show a positive correlation between BRCA1 and CD44, HAS2, HAS3 and HYAL1 in colorectal but not breast cancer." (PMID 32610620, 2020). "To further define the respective role of ERα and ERβ in HYAL1 regulation, we generated stable clonal lines using ER-negative human breast cancer MDA-MB-231 cells, which are positive for HYAL1, and in which ERα (231-ERα) or ERβ (231-ERβ) was stably expressed and functional." (PMID 27764788, 2016). "Furthermore, we observed a reduction of HYAL1 expression in response to estrogen in ERα-positive breast cancer cells and to ectopic expression of ERα in ERα-negative cells." (PMID 27764788, 2016). "This negative regulation of HYAL1 by ERα provides a mechanism supporting the specific inverse correlation we found between ESR1 and HYAL1, but not with HYAL2 or HYAL3 in the METABRIC cohort consisting of 1980 cases of breast cancer." (PMID 27764788, 2016). "However, based on recent evidence showing that EZH2 can be transcriptionally induced by estrogen in breast cancer cells, this might provide a mechanism by which the methylation of H3K27 can be promoted by estrogen in conjunction with the direct recruitment of ERα at the HYAL1 ERE-900." (PMID 27764788, 2016). "However, in the case of HYAL1, we found that mRNA levels significantly decrease in TT in breast cancer respect to NAT, while in colorectal cancer there is a tendency for HYAL1 to decrease in NAT respect to TT although not statistically significant." (PMID 32610620, 2020). "Consistent with the inverse correlation of HYAL1 and estrogen, MCF-7 and BT-474 cells showed reduced basal levels of HYAL1 protein when compared to ERα-negative breast cancer MDA-MB-231 and ovarian epithelial cancer TOV21G cells, which are both strongly positive for HYAL1." (PMID 27764788, 2016).
prostate carcinoma (18 papers, 2011 to 2025). A carcinoma that arises from epithelial cells of the prostate gland. "Clinical studies have demonstrated that elevated HYAL1 expression is significantly associated with invasive prostate cancer and serves as an independent predictor of biochemical recurrence following radical prostatectomy." (PMID 41421148, 2025). "Its biological activity has been tested in prostate cancer cells where it inhibits the activity of HYAL1, causing significant decrease in the proliferative and invasive cell capacities." (PMID 33809973, 2021). "Work published from our laboratory in bladder and prostate cancer systems, and which was later confirmed by other laboratories, has shown that HYAL-1 and the tumor-associated HA-HAase system promote tumor growth, invasion/metastasis and angiogenesis." (PMID 27419371, 2017). "Previous reports have shown that increased expression of hyaluronan and HYAL-1 were associated with high grade bladder and prostate cancers." (PMID 21695196, 2011). "Among the HYAL isoforms, HYAL1 has been identified in EVs associated with prostate cancer." (PMID 40214422, 2025). "Together, these studies suggest HYAL1 as a cell progression factor in prostate cancer via the promotion of proliferation, motility, and metastasis." (PMID 40214422, 2025). "Consistent with these in vivo findings, human prostate cancer cells stably overexpressing HYAL1 exhibited significantly increased migratory and proliferative capacities in vitro." (PMID 41421148, 2025). "Notwithstanding, future studies are required to validate the current findings and investigate the relevance of HYAL1 to prostate cancer cell survival before a conclusion can be reached on its mechanistic relevance." (PMID 40214422, 2025). "For example, in prostate cancer cell lines, HYAL1 functions as an oncogene or a tumor suppressor, depending on the HYAL1 levels." (PMID 37296612, 2023). "Our findings are in contrast to the findings in prostate cancer, where HYAL1 overexpression was shown to induce apoptosis." (PMID 37296612, 2023). "HYAL1 is observably overexpressed and can also be utilized as a predictor of recurrence in prostate cancer." (PMID 37568202, 2023). "Reducing HYAL-1 expression in bladder and prostate cancer cells inhibits tumor development and decreases their capacity to metastasize by triggering cell cycle arrest in the G2/M phase." (PMID 36613567, 2022). "Exosomes secreted by prostate tumor cells contain a protein hyaluronidase 1 (Hyal1) which promotes the migration of prostate stromal cells; in effect enhancing prostate cancer progression." (PMID 33805398, 2021). "Active HYAL1 is present in exosomes of prostate cancer cells and enhances cell motility by engaging FAK-mediated integrin signaling, possibly priming the nearby stromal cells into a pro-invasive phenotype." (PMID 33809973, 2021). "Of these molecules, the inhibition of HYAL1 enzyme was shown to decrease prostate cancer progression in vivo." (PMID 24454496, 2013). "Furthermore, the vesicular localization of HYAL1 within prostate cancer cells has also been shown to require its enzymatic function." (PMID 41421148, 2025). "Researchers have further delineated the intracellular trafficking route of HYAL1 in prostate cancer cells: the enzyme is initially secreted into the extracellular space via the classical ER-Golgi pathway, then re-internalized through endocytosis and incorporated into the vesicular sorting system." (PMID 41421148, 2025). "Finally, a correlation between high coexpression of HAS2 and HYAL1 and strong tumour growth and angiogenesis was observed for prostate carcinoma." (PMID 35767191, 2022). "A functional Sp1 binding element has been correlated with low HYAL1 expression in bladder and prostate cancer cells, suggesting that Sp1 might impair the promoter activity of HYAL1." (PMID 27764788, 2016). "Furthermore, Hyal-1 expression in cancer cells themselves functioned as both a tumor promoter and tumor suppressor in prostate carcinoma." (PMID 26029216, 2015).
prostate carcinoma (continued). "Interestingly, in a mouse model of prostate cancer, co-expression of a hyaluronidase (HYAL1) and a hyaluronan synthase (HAS2) significantly increased angiogenesis." (PMID 23560496, 2013). "Interestingly, levels of hyaluronan and HYAL-1 are reported to be elevated in urine of patients with bladder cancers and HYAL-1 has been shown to be secreted to the culture medium by some bladder and prostate cancer cell lines." (PMID 21695196, 2011). "Also, HYAL1 has been reported to be overexpressed in prostate cancer." (PMID 40214422, 2025). "Overexpression of HAS1 in prostate cancer was shown to be anti-tumorigenic; however, overexpression of both HAS1 and Hyal-1 increased HA fragmentation that in turn promoted tumor cell proliferation and metastasis." (PMID 26029216, 2015). "HYAL-1 and HYAL-2 are upregulated in prostate cancer, bladder cancer, and melanoma." (PMID 36613567, 2022). "The presence of hyaluronidase Hyal1 in prostate cancer-derived EVs stimulate the prostate stromal cell motility by engaging FAK-mediated integrin signaling, indicating that the elevated Hyal1 promotes prostate cancer progression." (PMID 30322133, 2018). "In addition, in prostate carcinoma HAS3 and HAS2 have been shown to produce HA that is broken down by Hyal1 and that subsequently drives tumour progression and even metastasis." (PMID 21429221, 2011). "However, except for our previous study on prostate cancer models, HYAL-1 and/or HAase activity have not been targeted in other preclinical models." (PMID 27419371, 2017). "As such HYAL-1 might play a role in tumor proliferation and cell cycle progression in ER-negative clear cell and mucinous EOC much in the same way as has been shown for ER-negative breast cancer and for bladder and prostate cancer cell lines." (PMID 21695196, 2011).